RNU6-484P (RNA, U6 small nuclear 484, pseudogene)
Gene: Small nuclear RNA gene on chromosome 5 (37,700,331 to 37,700,437, reverse strand). Ensembl gene ENSG00000206743.
Homologues: Orthologues: chimpanzee U6 (99% identical), macaque U6 (93% identical), rat LOC120097304 (81% identical), pig U6 (79% identical). Paralogues in human: RNU6-144P (89% identical), RNU6-20P (89% identical), RNU6-1145P (88% identical), RNU6-140P (88% identical), RNU6-16P (88% identical), RNU6-25P (88% identical), RNU6-41P (88% identical), RNU6-812P (88% identical), RNU6-1 (87% identical), RNU6-1179P (87% identical), RNU6-11P (87% identical), RNU6-15P (87% identical), and 1286 more.